UGT1A1 (UDP glucuronosyltransferase family 1 member A1)
Diseases named in the same sentence as UGT1A1 in open-access papers (continued):
Sharing a sentence is not in itself a finding about the gene and the disease.
colorectal cancer (continued). "In a retrospective study of 42 consecutive Japanese patients with advanced colorectal cancer between April 2005 and December 2009 at Saitama Medical University Hospital and International Medical Center, genotyping revealed UGT1A1 in 24 patients, and UGT1A1-6/UGT1A1-28 in 18 patients." (PMID 40432911, 2025). "Therefore, UGT1A1 genotyping saves costs for Chinese patients with colorectal cancer." (PMID 35340156, 2022). "SCO-101 has previously been studied together with chemotherapy in patients with colorectal cancer, where the compound counteracts resistance to irinotecan by inhibiting the drug efflux pump ABCG2 and the metabolic liver enzyme UGT1A1." (PMID 40272619, 2025). "According to the guideline of Chinese Society of Clinical Oncology (CSCO) for colorectal cancer in 2024, it is recommended to decrease the dose of CPT-11 for patients carrying the homozygous or double heterozygous for UGT1A1*28 or UGT1A1*6." (PMID 39877392, 2024). "Given the significant impact of colorectal cancer and the therapeutic implications of DPYD and UGT1A1 genotyping, it is understandable that medical oncology had the highest demand for PGx testing services in this study." (PMID 37927587, 2023). "For example, irinotecan is commonly used for treating colorectal cancer (COAD), and its active metabolite, SN-38, is primarily glucuronidated by UGT1A1 with weak activity from all other UGT1As except UGT1A4." (PMID 36428799, 2022). "The UGT1A1*6, UGT1A7*3 and UGT1A9*22 genotypes were shown to be related to severe toxicity concordant with a Japanese study of FOLFIRI-treated colorectal cancer patients." (PMID 36239106, 2022). "Thus, the aim of this study was to assess the allele and genotype frequencies and the relationship between CYP3A4/5, DPYD, UGT1A1, ABCB1, and ABCC2 genetic variations and irinotecan-induced toxicity in Thai colorectal cancer patients." (PMID 32778670, 2020). "UGT1A1 is expressed in colorectal cancer, and p-cresol and indoxyl sulfate inhibit the function of UGT1A119,20; therefore, further research is needed to evaluate the effects of USR on the function of UGT1A1." (PMID 31664047, 2019). "We designed a prospective observational study to evaluate the effects of UGT1A1 genotypes and non-genetic factors on the efficacy and safety of irinotecan-based regimens in Japanese patients with advanced colorectal cancer." (PMID 25880011, 2015).
Crigler-Najjar syndrome (36 papers, 2013 to 2026). Crigler-Najjar syndrome (CNS) is a hereditary disorder of bilirubin metabolism characterized by unconjugated hyperbilirubinemia due to a hepatic deficit of bilirubin glucuronosyltransferase (GT) activity. "Crigler-Najjar syndrome is a rare disorder caused by UGT1A1 mutations that results in neurotoxic and potentially fatal hyperbilirubinemia and jaundice." (PMID 36936447, 2023). "Crigler-Najjar syndrome is an ultra-rare disorder of bilirubin metabolism caused by mutations in the uridine diphosphate glucuronosyl transferase 1A1 (UGT1A1) gene." (PMID 36936447, 2023). "A genetic disorder caused by a defective UGT1A1 (UDP glucuronosyltransferase family 1 member A1) enzyme leads to Crigler–Najjar syndrome (CNS) and can also cause BIND." (PMID 37759499, 2023). "In rare instances, UGT1A1 genetic variants can result in almost complete loss of UGT1A1 function leading to high levels of unconjugated bilirubin that cause severe and debilitating symptoms described as Crigler–Najjar syndrome." (PMID 33805415, 2021). "Crigler-Najjar syndrome (CNS) is characterized by a severe unconjugated hyperbilirubinemia caused by variants in the UGT1A1 gene." (PMID 32211025, 2020). "We have previously detailed a patient with clinically diagnosed Crigler-Najjar syndrome type II caused by multiple allelic variants in the UGT1A1 gene." (PMID 32211025, 2020). "A UGT1A1-encoding vector can be used to correct UGT1A1 deficiency, as seen in Crigler-Najjar syndrome." (PMID 29766030, 2018). "Crigler-Najjar syndrome is an inherited disorder of bilirubin metabolism that is caused by the absence of uridine diphosphate glucuronosyl transferase 1A1 (UGT1A1) activity." (PMID 30112420, 2018). "Five variants in UGT1A1 gene causing Crigler-Najjar syndrome, type I/II were detected in four unrelated patients (3 homozygous and 1 compound-heterozygous), while two unrelated patients were reported with two disease causing variants in the ABCC2 gene causing Dubin-Johnson syndrome." (PMID 41165782, 2025). "UGT1A1*27 is described as a substitution of cytosine by adenine, changing amino acid 229 from proline to glycine, and its mutations may have phenotypically severe jaundice classified as Crigler–Najjar syndrome." (PMID 36128448, 2022). "In our model, the mean Vmax of UGT1A1 for Crigler‐Najjar syndrome was reduced to 0.55 μmol/L/min (0.09% of healthy‐state value), which is consistent with literature." (PMID 41543361, 2026). "Sensitivity analysis of rate constants shows that, in Gilbert and Crigler‐Najjar syndromes, UB plasma levels are primarily influenced by UGT1A1, whereas CB levels are mostly affected by OATP1B1‐mediated uptake." (PMID 41543361, 2026). "In the subsequent study, individuals diagnosed with Crigler–Najjar syndrome successfully restored the expression of the liver enzyme UGT1A1 with the application of gene therapy." (PMID 40521034, 2025). "The i705-C2 iPSCs-derived HLCs retained defective UGT1A1 expression, as the cells were derived from the Crigler–Najjar syndrome (CNS) patient." (PMID 37759499, 2023). "A potential approach to treating Crigler-Najjar syndrome is systemic delivery of a gene therapy vector expressing UGT1A1, which would enable the liver to continuously synthesize UGT1A1." (PMID 30112420, 2018). "The functionality of the consensus sequence is recognized in UGT1A1, where point mutations within this region have been attributed to Crigler–Najjar Syndrome, a metabolic disease resulting from reduced or absent UGT1A1 activity." (PMID 38474028, 2024). "Crigler–Najjar syndrome (CNS) is an ultra-rare autosomal recessive disorder caused by several known variants in the UDP-glucuronosyltransferase 1A1 (UGT1A1) gene, leading to a lack or absence of activity of its encoded enzyme." (PMID 37761392, 2023).
Crigler-Najjar syndrome (continued). "The iPSC-derived cortical organoids employed in this study represent a Crigler–Najjar syndrome model to study defective UGT1A1 and its subsequent phenotypic manifestation and potential application for future BIND-associated toxicological studies and drug screening." (PMID 37759499, 2023). "For Crigler-Najjar syndrome type II, the functional activity of UGT1A1 is below 10%." (PMID 32211025, 2020). "These serum bilirubin levels without any treatment are in line with those seen in Crigler-Najjar syndrome (CNs) type II, indicating a partial deficiency of UGT1A1." (PMID 31142299, 2019). "Genetic variation in UGT1A1 is involved in inherited disorders of bilirubin metabolism such as Crigler-Najjar syndrome, which is manifested in complete absence (type 1) or diminished (types 2–3) bilirubin glucuronidation and resulting impaired bilirubin excretion." (PMID 26091520, 2015). "Crigler-Najjar syndrome is an inherited disorder caused by a lack of the gene UGT1A1." (PMID 40521034, 2025). "Also family segregation data from our previous study suggested that each of the variants separately did not reduce UGT1A1 enzyme activity enough to cause Crigler-Najjar syndrome type II." (PMID 32211025, 2020). "Crigler–Najjar Syndrome (CNS) with residual activity of UDP-glucuronosyltransferase 1A1 (UGT1A1) and no need for daily phototherapy is called mild Crigler–Najjar Syndrome." (PMID 37761392, 2023).
Jaundice (27 papers, 2012 to 2026). Yellow pigmentation of the skin due to bilirubin, which in turn is the result of increased bilirubin concentration in the bloodstream. "The allele frequency of the c.211G > A variant of UGT1A1*6 in the prolonged jaundice group was 58.9% while it was 21.5% in the control group (χ2 = 50.15, P < 0.001)." (PMID 36605758, 2022). "Our results showed that the allele frequency of UGT1A1*6 was significantly different between the prolonged jaundice group (58.9%; 103/175) and the control group (21.5%; 32/149)." (PMID 36605758, 2022). "Our results show that exclusive breastfeeding, GA 35~37 w, previous phototherapy, and gene variant of G to A at nt 211 of UGT1A1 are risk factors of jaundice for healthy infants at one month of age." (PMID 30287871, 2018). "In this study, G to A variant at nt 211 in UGT1A1 was associated with prolonged jaundice, which is consistent with a number of previous reports showing G to A variant at nt 211 in UGT1A1 as a risk factor of prolonged jaundice in breastfed infants." (PMID 30287871, 2018). "Many studies have documented the strong association between breast milk jaundice and gene variants of TA repeat or nucleotide (nt) 211 in UGT1A1 promoter." (PMID 30287871, 2018). "This UGT1A1 mutation is known to be related to diverse diseases and to elevate the risk of jaundice and gallstones." (PMID 23388413, 2013). "We speculated that this preterm infant with carrying the G71R polymorphism reduced UGT1A1 activity and developed severe jaundice that was likely triggered by factors such as breast feeding and medications." (PMID 23388413, 2013). "Thus, our data cannot determine whether gene variant at nt 211 in UGT1A1 is associated with prolonged jaundice among infants fed with formula." (PMID 30287871, 2018). "The UDP glucuronosyltransferase 1A (UGT1A1) genotyping was conclusive in the case of jaundice and cholelithiasis." (PMID 32751969, 2020). "The authors suggested that pre-treatment screening for UGT1A1*28 genotype would reduce the prevalence of jaundice from 22% to 5%." (PMID 23680529, 2013). "This infant with low UGT1A1 activity developed severe jaundice that was likely triggered by factors such as breast feeding and medications." (PMID 23388413, 2013). "Indeed, UGT1A1 reaches normal adult activity by 3 months of age and jaundice typically resolves by this time, including in exclusively breastfeeding dyads." (PMID 38334089, 2024). "Is it possible that the improved jaundice outcomes observed in the F80 group resulted from enhanced conjugation of bilirubin due to the earlier exposure to fortifier components that switch on UGT1A1 expression in the neonatal intestine?" (PMID 32708857, 2020). "UGT1A1*28 allele was associated with jaundice in a study in which bilirubin levels were not measured." (PMID 22506127, 2012). "To study the mechanisms of bilirubin-induced neurological damage (BIND) in vivo, we generated a mouse model lacking the Ugt1a1 protein and, consequently, mutant mice developed jaundice as early as 36 hours after birth." (PMID 25062689, 2014).
breast carcinoma (23 papers, 2005 to 2026). "In this retrospective study, we sought to evaluate the associations between UGT1A1 status, toxicity, and therapeutic outcomes in sacituzumab recipients with advanced breast cancer who underwent genotype testing for UGT1A1 alleles (N = 68)." (PMID 39157928, 2024). "We wanted to determine if UGT1A1 polymorphisms are associated with less frequent discontinuations of therapy for progression and increased toxicity in patients with advanced breast cancer undergoing treatment with sacituzumab." (PMID 39157928, 2024). "Suggestive positive associations were observed between bilirubin levels, genetically predicted by non-UGT1A1 SNPs, and risk of breast cancer." (PMID 33671849, 2021). "In contrast to breast cancer, bilirubin levels predicted by the UGT1A1 SNP were inversely associated with risk of ovarian cancer overall and serous ovarian cancer." (PMID 33671849, 2021). "A meta-analysis of retrospective case-control studies (N cases = 5746, N controls = 8365) suggested that the UGT1A1*28 allele 7/7 genotype is a potential risk factor for breast cancer in Caucasians." (PMID 33671849, 2021). "There was a suggestive positive association between bilirubin levels, genetically predicted by non-UGT1A1 SNPs, and risk of breast cancer, in particular of the ER positive subtype (OR 1.12, 95% CI 1.03–1.22 after removing potential pleiotropic SNPs)." (PMID 33671849, 2021). "In agreement with the largest meta-analyses of epidemiological studies to date, we did not observe an association for SHBG rs6259, PGR rs1042838, ESR1 rs2234693, CYP19 rs10046 and rs4775936, and UGT1A1 rs8175347 and breast cancer risk." (PMID 23935996, 2013). "A total of 57 breast cancer cases and 35 controls were genotyped for the UGT1A1 TATA box promoter polymorphism." (PMID 30349745, 2012). "In breast cancer cases with the UGT1A1*28/*37 genotype, which represents low activity alleles, the mean UGT1A1 mRNA levels was lowest (0.01 ± 0.02)." (PMID 30349745, 2012). "In support of our findings, a large population study demonstrated that the UGT1A1 (TA) repeat promoter polymorphism was significantly associated with increased breast cancer risk in postmenopausal women." (PMID 30349745, 2012). "As with SULT1A1, several studies have reported links between the UGT1A1 polymorphism and the risk of breast cancer." (PMID 16280036, 2005). "A recent study of a Chinese population suggested that UGT1A1*28 was associated with an increased risk of breast cancer in women younger than 40 years old (OR = 1.7, 95% CI = 1.0–2.7)." (PMID 16280036, 2005). "In fact, several studies have shown that increased estrogen activities due to UGT1A1 polymorphisms may be associated with an increased risk of breast cancer, although this phenomenon is still controversial." (PMID 34168201, 2021). "Therefore, we aimed to investigate possible associations between germline genetic polymorphisms within GSTM1, GSTT1, GSTP1, SULT1A1 and UGT1A1 genes and breast cancer clinicopathological characteristics together with disease progression." (PMID 25648141, 2015). "However, despite the relationship between these SNPs and estrogen levels, most studies, including our own, have not observed any association between these SNPs in CYP19 and UGT1A1 and breast cancer risk." (PMID 23935996, 2013). "Since UGTs are highly polymorphic, determining whether the UGT1A1 promoter polymorphism may have an impact on clinicopathological factors, is crucial for determining breast cancer risk, treatment response, and clinical outcome of the patient." (PMID 30349745, 2012). "Therefore, we investigated the effect of the UGT1A1 (TA) repeat promoter polymorphism on UGT1A1 mRNA expression among breast cancer cases compared to controls." (PMID 30349745, 2012).
breast carcinoma (continued). "Collectively, our research findings suggest that UGT1A1 may be an important component for determining breast cancer risk as it relates to stage, menopausal status and ethnicity; however, additional studies are warranted to confirm these findings." (PMID 30349745, 2012). "Given the role of SULT1A1 and UGT1A1 in the metabolism of estrogens, we hypothesized that polymorphisms in these genes might be associated with differences in breast tumor characteristics, such as tumor size, tumor grade and age of breast cancer diagnosis." (PMID 16280036, 2005). "Considering the relationship between UGT1A1 polymorphisms, increased toxicities, and subsequent therapy discontinuation, it raises the possibility that pharmacogenomics may play a role in the adverse outcomes experienced by African American women with breast cancer." (PMID 39157928, 2024). "The number of TA repeats in the promoter of low activity UGT1A1 was reported to be protective against breast cancer in pre-menopausal Nigerian women." (PMID 33659210, 2020). "The interindividual differences observed for UGT1A1 mRNA expression in breast cancer tissues compared to normal breast tissues with respect to ethnicity, menopausal status, and stage of breast disease further suggest that genetic variations or promoter polymorphisms in UGT1A1 may be involved." (PMID 30349745, 2012). "Our study demonstrated that UGT1A1 gene expression is decreased in breast cancer cases in comparison to controls in AA and EA female donors who have either the UGT1A1*1/*1, UGT1A1*1/*28, UGT1A1*28/*28, or the UGT1A1*28/*37 genotype." (PMID 30349745, 2012). "We observed that the UGT1A1*1/*1 was most prevalent among breast cancer cases (58%) and controls (57%), followed by UGT1A1*28/*28 (Cases: 23%, Controls: 17%)." (PMID 30349745, 2012). "UGT1A1 mRNA down-regulation was strongly correlated with postmenopausal status in breast cancer versus controls (p = 0.04)." (PMID 30349745, 2012). "In all the UGT1A1 genotypes observed in our study, the mean mRNA levels was significantly decreased among breast cancer cases as compared to controls for UGT1A1*1/*1 (p = 0.004), UGT1A1*28/*28 (p = 0.03) and UGT1A1*28/*37 (p = 0.06)." (PMID 30349745, 2012). "In all UGT1A1 genotypes observed in our study, the mean UGT1A1 mRNA expression levels was significantly decreased among breast cancer cases as compared to controls (p=0.04)." (PMID 30349745, 2012). "Of the UGTs analyzed, the mean UGT1A1 mRNA expression levels were significantly lower in breast cancer specimens as compared to normal breast tissues (Tumor: 0.5 ± 0.2; Normal: 4.1 ± 1.3, p = 0.0006)." (PMID 30349745, 2012). "Additionally, our single‐center ancestry‐genotypic frequencies for UGT1A1 in sacituzumab recipients with breast cancer align with past studies that investigated the prevalence of UGT1A1*28 across races and ethnicities." (PMID 39157928, 2024). "In the present study, we demonstrated that genetic variants of the host, such as SNPs of MAP3K1, CYP2B6, UGT1A1, HCN1, ABCB1, and ALDH3A1, may worse the prognosis of HR-positive breast cancer patients, predominantly for premenopausal women." (PMID 28178648, 2017). "We did not observe an association between potential functional genetic polymorphisms in the estrogen pathway, SHBG rs6259, ESR1 rs2234693, CYP19 rs10046 and rs4775936, and UGT1A1 rs8175347, or the progesterone pathway, PGR rs1042838, with the risk of breast cancer." (PMID 23935996, 2013). "However, there was a significant difference in UGT1A1 mRNA in postmenopausal women breast cancer cases compared to controls (Tumor: 0.3 ± 0.2; Normal: 2.2 ± 1.9, p = 0.04)." (PMID 30349745, 2012). "Furthermore, among all UGT1A1 genotypes identified, the mean UGT1A1 transcript levels were significantly decreased among breast cancer cases compared to controls (p=0.04)." (PMID 30349745, 2012). "UGT1A1, previously linked to MD and breast cancer, is not represented on the microarray used in this study." (PMID 20799965, 2010).